FGFR2 (fibroblast growth factor receptor 2)
Diseases named in the same sentence as FGFR2 in open-access papers (continued):
Sharing a sentence is not in itself a finding about the gene and the disease.
triple-negative breast carcinoma (20 papers, 2010 to 2025). An invasive breast carcinoma which is negative for expression of estrogen receptor (ER), progesterone receptor (PR), and human epidermal growth factor receptor 2 (HER2). "As an oncogene, FGFR1 deletion is less understood, while FGFR2 (10q26) missense mutation may be indicative of anti-FGFR2 inhibitor, as amplification or overexpression of FGFR2 was observed in 4% of triple negative breast cancers." (PMID 34203389, 2021). "For instance, Wu and colleagues showed that the use of the FGFR2 inhibitor erdafitinib increased T-cell infiltration in immunocompetent mouse models of triple-negative breast cancer." (PMID 39969434, 2025). "Fibroblast growth factor receptor 2 (FGFR2) is also a promising target for TTCs, with amplifications in FGFR2 observed in a subset of triple-negative breast cancers (TNBCs)." (PMID 36726355, 2022). "From a clinical perspective, patients harbouring triple-negative breast cancers that exhibit amplified FGFR2 are potential candidates for receiving treatment with an FGFR kinase inhibitor." (PMID 32409632, 2020). "We used a SILAC quantification approach to compare the proteomes of the FGFR2-overexpressing triple-negative breast cancer cell lines SUM52 and MFM223." (PMID 32409632, 2020). "FGFR2 amplification is also detected in 5% of triple-negative breast cancers, providing the possibility of specific targeted therapy when many other options are less efficacious by the nature of the disease profile." (PMID 28030802, 2017). "We observed FGFR2 amplification exclusively in patients with triple-negative breast cancer (3 patients), consistent with previous reports." (PMID 27489863, 2016). "In order to address this, we used SILAC-based quantitative phosphoproteomics to identify phosphorylation events that changed within the two FGFR2-overexpressing triple-negative breast cancer cell lines MFM223 and SUM52 upon treatment with the FGFR inhibitor SU540232." (PMID 32409632, 2020). "A phase I dose-escalation trial in patients with advanced stage solid tumors known to express FGFR2 had initially set out to establish a MTD in two cohorts, those with triple negative breast cancer and a second group to encompass other tumors expressing FGFR2 (NCT02368951)." (PMID 28030802, 2017). "Finally, examining the subset of triple negative breast cancer cell (TNBC) lines, we show that a downstream target of FGFR2, a recently implicated oncogene in TNBC, COL1A1 is frequently affected by MCD even though in FGFR2 itself is rarely affected." (PMID 20478067, 2010). "Phosphoproteomic profiling across 18 triple-negative breast cancers (TNBC) and 1 luminal B PDX revealed considerable heterogeneity in kinase activation, but 1/3 of PDX exhibited enhanced phosphorylation of FGFR1, FGFR2 or FGFR4." (PMID 34344433, 2021).
lung adenocarcinoma (18 papers, 2013 to 2026). A carcinoma that arises from the lung and is characterized by the presence of malignant glandular epithelial cells. "Our results are consistent with previous findings obtained in lung adenocarcinoma and suggest that cell invasion in this context involves a crosstalk between FGFR2 and TRPA1, which implies a pore-independent function of the channel." (PMID 38339360, 2024). "TRPA1 interaction with fibroblast growth factor receptor 2 (FGFR2) induces the activation of the receptor, promoting cancer cells’ proliferation and invasion, prompting lung adenocarcinoma metastasisation to the brain." (PMID 35806388, 2022). "We also observed 1 gene rearrangement event involving FGFR2 and an internexin neuronal intermediate filament protein α gene (INA) fusion (FGFR2 F17: INA I2) in a patient (P16) with stage IV lung adenocarcinoma." (PMID 33710807, 2021). "Astrocyte-derived exosomes can transfer miRNA-142-3p to lung adenocarcinoma cells and inhibit brain metastasis by suppressing fibroblast growth factor receptor 2 activation." (PMID 32337272, 2020). "Briefly, among newly detected mutations in lung adenocarcinoma, AKT, BRAF, FGFR2, HRAS, and KIT mutations were detected in one sample (1.3%), MAP2K in two samples (2.6%), MET in 4 samples (5.9%), and FGFR3 in 5 samples (7.4%)." (PMID 28404952, 2017). "In agreement with this hypothesis, TRPA1 can physically associate with the fibroblast growth factor receptor 2 (FGFR2) via its NH2-terminal ARD and thereby stimulate lung adenocarcinoma (LUAD) progression and metastatic spreading in a Ca2+-independent manner." (PMID 37174661, 2023). "Finally, a single case of a fusion between FGFR2 and citron Rho interacting kinase (FGFR2-CIT) was identified in a lung adenocarcinoma patient by the Cancer Genome Atlas project." (PMID 34068816, 2021). "FGFR2 is described as a prognostic marker of recurrence in lung adenocarcinoma." (PMID 31027181, 2019). "FGFR2 and other FGFR kinase family gene alterations have been found in both lung squamous cell carcinoma and lung adenocarcinoma." (PMID 38791306, 2024). "Experiments performed on lung adenocarcinoma cells proposed a bold hypothesis: the N-terminal ankyrin repeats of TRPA1 directly bind to the C-terminal proline-rich motif of the fibroblast growth factor receptor 2 (FGFR2), inducing the activation of the receptor through the MAP kinase pathway." (PMID 37507867, 2023). "Our observations represented the first case of a FGFR2-INA fusion in NSCLC, in particular, lung adenocarcinoma." (PMID 33710807, 2021). "Similarly, FGFR2 mutations residing in the gene's kinase domain are a frequent observation in human non-small cell lung cancers, even in the absence of prior CS exposure, and led to lung adenocarcinoma formation in conditional knock-in mice." (PMID 35295134, 2021). "In addition, in lung adenocarcinoma, direct binding of TRPA1 to FGFR2 resulted in a constitutive receptor activation, thereby promoting tumor progression." (PMID 34440820, 2021). "Interestingly, among seven SNF5-deficient non-MRT lines, two of them, the rhabdomyosarcoma line KYM1 and the lung adenocarcinoma line HLC1, also displayed high levels of FGFR1 and FGFR2 transcripts, respectively, which were abrogated upon reconstitution of SNF5." (PMID 24204904, 2013).
glioblastoma (16 papers, 2017 to 2024). The most malignant astrocytic tumor (WHO grade IV). "Of these, PAI-1/SERPINE1 and MMP16 showed pathogenic mutations in the FGFR2 tumors, a novel finding in glioblastoma." (PMID 33853673, 2021). "In conclusion, we discovered novel targetable mutations in the FGFR glioblastoma subgroup, including FGFR2 alterations occurring during the evolution of a multifocal and unusually aggressive IDH-mutant astrocytoma." (PMID 33853673, 2021). "Informatics analyses revealed that a low expression of FGFR2 mRNA was significantly associated with poor prognosis in prostate adenocarcinoma, cervical squamous cell carcinoma, and glioblastoma multiforme." (PMID 30837551, 2019). "Furthermore, PTEN tyrosine 240 phosphorylation by FGFR2 (fibroblast growth factor receptor 2) also causes glioblastoma (GBM) cells to become more radioresistant and epidermal growth factor receptor tyrosine kinase inhibitor resistant." (PMID 36830628, 2023). "In glioblastoma cases from The Cancer Genome Atlas (TCGA), FGFR2 is most commonly deleted and several FGFR2 fusion genes have been identified, including CXCL17–FGFR2, SIPA1L3–FGFR2, FGFR2–SIPA1L3 and FGFR2–CEACAM1." (PMID 37857607, 2023). "Here, we investigated the distribution and functional relevance of FGFR1 and FGFR2 in human glioblastoma xenograft models." (PMID 37579831, 2023). "Comparative analysis of RNA-sequencing data of FGFR1 and FGFR2 knockdown glioblastoma cells revealed a FGFR1-specific gene regulatory network associated with tumor invasion." (PMID 37579831, 2023). "The most common tumors with FGFR2 CNVs were glioblastoma multiforme (GBM) (87.0%), KICH (76.9%), UCS (70.2%), LUSC (60.6%), and OV (60.0%)." (PMID 33968743, 2021). "Alternatively, we report the first case of glioblastoma with TERT amplification accompanied by multiple TERT and FGFR2 gene fusions instead of TERTp mutation." (PMID 34976798, 2021). "Loss of FGFR1, but not FGFR2, significantly reduced cell migration in vitro and tumor invasion in human glioblastoma xenografts." (PMID 37579831, 2023). "Additional loss of chromosome arm 10q is seen in over 75% of IDH-wild-type glioblastoma and usually spans the PTEN locus at 10q23.31, and in 60% of IDH-mutant glioblastoma cases, the most commonly deleted region being 10q25-qter, encompassing the FGFR2 and DMBT1 loci." (PMID 33853673, 2021). "Although most IDH-mutant cases conform to this biological behavior, we describe here the first case of de novo IDH-mutant glioblastoma with FGFR2 alterations that induced fulminant progression with LM spread, resembling the most aggressive cases of IDH-wild-type glioblastoma." (PMID 33853673, 2021). "While little is known about the role of FGFR2 and FGFR4 in glioblastoma, FGFR1 is expressed in human glioma, and its expression level increases with the grade of malignancy." (PMID 35955806, 2022). "RTK genes are frequently altered in glioblastomas; in fact, at least one RTK is altered in 65–75% of glioblastomas (EGFR (50–58%), PDGFRA (12–15%), MET (2–3%), and FGFR2/3 (3%))." (PMID 30279357, 2018). "Given this, we sought to uncover and characterise the PRM interactome of the RTKs epidermal growth factor receptor (EGFR), FGFR2 and ERBB2/HER2 in cell lines resembling oesophageal adenocarcinoma (OAC), breast adenocarcinoma (BrAC), glioblastoma (GBM) and lung squamous cell carcinoma (LSCC)." (PMID 39165974, 2024). "In two cases, the identification of entity-specific fusions suggested a re-classification of a meningioma CNS-WHO grade 2 to intracranial mesenchymal tumor (ATF1::ESWR1 fusion) and glioblastoma to a polymorphous low-grade neuroepithelial tumor of the young (PLNTY, FGFR2::CTNNA3 fusion)." (PMID 39143272, 2024). "•We find that FGFR1 is present on invasive glioblastoma cells, whereas FGFR2 is absent in these cells and only expressed in the tumor mass." (PMID 37579831, 2023).
glioblastoma (continued). "Although antibodies targeting FGFR2 (bemarituzumab, NCT03694522) and FGFR3 (vofatamab, NCT03123055; LY3076226, NCT02529553; MFGR1877S, NCT01363024) are in clinical trials for other cancers, these have yet to be considered for glioblastoma." (PMID 37857607, 2023). "A whole genome analysis of more than 2662 adult human glioblastoma samples revealed the number of FGFR-aberrations and amplifications as generally sparse, with prevalence of FGFR1 aberrations of 51 in 3068, FGFR2 in 12 of 2662, FGFR3 in 13 of 2887, and FGFR4 in 9 out of 2456 investigated samples." (PMID 35955806, 2022). "FGFR2-fusions are the most frequent FGFR-fusions in solid cancer and can be found in cholangiocarcinoma, breast cancer, prostate cancer, thyroid cancer, lung cancer, bladder cancer, oral and head and neck cancer, as well as in glioblastoma." (PMID 35955806, 2022). "All FGFR3 glioblastoma cases showed chromosome 10 deletion, and the overlap with the F48 10q23.31-qter deletion represented the only common CNV alteration between the FGFR3 and FGFR2 glioblastomas." (PMID 33853673, 2021). "We found FGFR1, but not FGFR2, expressed in invasive glioblastoma cells." (PMID 37579831, 2023). "We characterized in this study a spectrum of FGFR alterations from a cohort of 101 WHO grade IV diffuse gliomas, including novel FGFR2 and FGFR3 fusions, the former taking place in IDH-mutant glioblastoma, a neoplasm previously not known to harbor oncogenic FGFR alterations." (PMID 33853673, 2021).
colon cancer (14 papers, 2013 to 2025). "Four mutational hotspots in the Immunoglobulin I-set domain of FGFR2 were observed in colon cancer, which hints at a tumor suppression role for FGFR2 in colon cancer." (PMID 25794154, 2015). "We observed a significantly elevated expression of the Fibroblast Growth Factor Receptor 2 (FGFR2) in tumour compartments of relapsed colon cancer stage II patients." (PMID 37543577, 2023). "Overexpression of C1GalT1 in colon cancer cells changed the O-glycan structures of FGFR2, which enhanced FGFR2 interaction with bFGF- and bFGF-mediated malignant phenotypes." (PMID 34944925, 2021). "A risk scoring system consisting of eight IRGs (FGFR2, ZC3HAV1L, TNFRSF11B, CD79A, IGHV3-11, IGHV3-21, IGKV2D-30, and IGKV6D-21) was constructed to evaluate the prognosis of colon cancer patients based on multivariate Cox analysis." (PMID 34938284, 2021). "We conclude that in our panel of colon cancer cell lines that FGFR2 is highly overexpressed and activated only in NCI-H716 cells." (PMID 24968263, 2014). "C1GALT1 overexpression enhances the invasive potential and stem-like cell property of colon cancer cells via modifying O-glycosylation and activity of FGFR2." (PMID 24758762, 2014). "Due to overexpression of FGFR2 in numerous tumours and its significant role in progression and tumorigenesis, FGFR2 could be a promising target for treatment of stage II colon cancer patients in future." (PMID 37543577, 2023). "Unsubstituted TF antigen occurs on FGFR2 in human colon cancer HCT116, SW620, and SW580 cells." (PMID 34944925, 2021). "The only report of FGFR2 amplification in CRC was from the NCI-H716 colon cancer cell line." (PMID 28835367, 2017). "However, arguing against a high frequency for FGFR2 amplification in ascites is that other colon cancer cell lines derived from ascites (Colo201, Colo205, and SKCO1) do not harbor FGFR2 amplification." (PMID 24968263, 2014). "In addition, we observed a small subset of colon tumor harbored FGFR2 overexpression that may result in growth dependency in the tumor cells." (PMID 24968263, 2014). "In this study, we found that FGFR2 could be pulled down by both VVA and PNA lectins and removal of sialic acids enhanced their binding to FGFR2, suggesting that FGFR2 carries short O-glycans, such as Tn, sialyl Tn, T, and sialyl T antigens in colon cancer cells." (PMID 24758762, 2014). "This is especially true for the three identified genes, MMP11, FGFR2 and OTOP2, which need validation in an equivalent stage II colon cancer cohort with conventional immunostaining procedures." (PMID 37543577, 2023). "We thereby identified FGFR2, MMP11 and OTOP2 as three differentially expressed genes in the neoplastic tissue predicting tumour recurrence in stage II colon cancer." (PMID 37543577, 2023). "This proof of principle study shows the potential of in situ sequencing revealing novel potential predictive biomarkers in colon cancer stage II, namely MMP11, FGFR2 and OTOP2, relevant for relapse of disease." (PMID 37543577, 2023). "We were able to identify FGFR2, MMP11 and OTOP2 as upregulated genes in tumour compartments of relapsed patients diagnosed with stage II colon cancer." (PMID 37543577, 2023). "Across the cohort, six fusion gene rearrangements were identified in cancers of the colon (TPM-NTRK1), bile duct (FGFR2), thyroid (BRAF) and prostate (ETV4-CLTC, and TMPRSS2-ERG)." (PMID 36213130, 2022). "A risk score system consisting of eight immune-related genes (IRGs) (FGFR2, ZC3HAV1L, TNFRSF11B, CD79A, IGHV3-11, IGHV3-21, IGKV2D-30, and IGKV6D-21) was constructed to predict the prognosis of colon cancer patients." (PMID 34938284, 2021). "FGFR2 gene amplification has only recently been documented in CRC, where it was identified in the NCI-H716 colon cancer cell line." (PMID 28835367, 2017). "We defined the prevalence of FGFR2 overexpression and amplification in primary colon cancer using immunohistochemistry (IHC) for FGFR2 expression and FISH for FGFR2 amplification." (PMID 24968263, 2014).
colon cancer (continued). "The modification of FGFR2 by C1GALT1, as evidenced by the presence of sTn on FGFR2, enhances its phosphorylation, promoting invasive behavior and cancer stem-like properties in colon cancer cells." (PMID 38699634, 2024). "Three differentially expressed genes (FGFR2, MMP11 and OTOP2) in the neoplastic tissue compartments of relapsed patients in comparison to non-relapsed patients were identified predicting recurrence in stage II colon cancer." (PMID 37543577, 2023). "Transfection of human colon cancer HCT116 and SW480 cells with C1GalT1 reduced the binding of Tn-binding lectin VVA to FGFR2 while knockdown C1GalT1 increased VVA binding to FGFR2 (indications of increased and reduced FGFR2 O-glycosylation, respectively) in the cells." (PMID 34944925, 2021). "We did not observe FGFR2 amplification in a tissue array of primary colon cancer but did find high expression in a subset of samples." (PMID 24968263, 2014). "Immunohistochemistry revealed FGFR2 overexpression in a subset of primary colon cancer, but we did not observe amplification." (PMID 24968263, 2014). "Importantly, FGFR2 and MMP11 are druggable targets in other cancer entities and could become novel predictive biomarkers in stage II colon cancer." (PMID 37543577, 2023).
lymph node metastasis (14 papers, 2014 to 2025). "FGFR2 amplification is significantly associated with lymph node metastasis, with 24% of FGFR2-amplified cases showing intratumoral heterogeneity." (PMID 37510761, 2023). "A meta-analysis found that FGFR2 protein overexpression was associated with deeper tumor invasion, higher rates of lymph node metastasis, more advanced stages, and worse outcomes." (PMID 37510761, 2023). "A meta-analysis published in 2019 concluded that high FGFR2 protein expression in GC was associated with worse outcomes, greater depth of invasion, higher rates of lymph node metastasis, and more advanced disease stage." (PMID 35167603, 2022). "Compared to FGFR2-unamplified GC, FGFR2-amp is significantly associated with lymph node metastasis and worse survival rate." (PMID 36210834, 2022). "FGFR2 IHC positivity was also significantly associated with tumor depth and lymph node metastasis (all P < 0.001) [Bonferroni-corrected P < 0.003 (= 0.05/16)]." (PMID 26933914, 2016). "FGFR2 amplification was frequently found in the aggressive diffuse subtype from Lauren’s classification, and associated with lymphatic and venous invasion, lymph node metastasis, distant metastasis, advanced TNM stage, and poor prognosis." (PMID 36147913, 2022). "In five cases, both the primary tumor and its lymph node metastasis showed concordant FGFR2 amplification." (PMID 36416959, 2023). "By univariate Cox regression analysis, older age, diffuse histological type, high grade, advanced stage, lymph node metastasis, and FGFR2 overexpression were correlated with unfavorable outcomes." (PMID 32934314, 2020). "In DGC, high expression of FGFR1, FGFR2, or FGFR4 was significantly associated with the depth of invasion, lymph-node metastasis, pathological stage, and distant metastasis or recurrent disease." (PMID 28056982, 2017). "In addition, the late TNM stage, large tumor size and lymph node metastasis were associated with an increased expression of AKT3 and FGFR2." (PMID 40057671, 2025). "Regardless of the FGFR2 status, premenopausal vs. postmenopausal patients were more frequently linked with lymph node metastases (P = 0.023), presence of DCIS component (P = 0.001) and chemotherapy in the adjuvant setting (P = 0.006)." (PMID 35726195, 2022).